IGFBP7 (insulin like growth factor binding protein 7)
Diseases named in the same sentence as IGFBP7 in open-access papers (continued):
Sharing a sentence is not in itself a finding about the gene and the disease.
cardiovascular disease (5 papers, 2016 to 2025). "In a long-term follow-up study of theelderly population in the community, insulin-like growth factor-binding protein-7(IGFBP7) levels were found to correlate with structural changes in the agingheart muscle and independently predicted cardiovascular disease risk." (PMID 39077479, 2023). "Notably, mutations and altered expression of IGFBP7 and FLNA have been observed in various cardiovascular diseases." (PMID 37036839, 2023). "In general, the concentrations of IGFBP7 and GDF-15 were lower than those reported in other studies, focused on patients with cardiovascular disease." (PMID 34217226, 2021).
cardiac diseases (4 papers, 2021 to 2023). "IGFBP7 and the other 2 biomarkers, GDF-15 and P1NP, were chosen since they covered different aspects of cardiac diseases, such as inflammation, apoptosis, fibrosis, and were described as specifically linked to one or more cardiac phenotypes." (PMID 34217226, 2021).
adenocarcinoma (3 papers, 2015 to 2025). A common cancer characterized by the presence of malignant glandular cells. "In contrast, positive IGFBP-7 expression in adenocarcinoma was associated with significantly reduced median and 5-year survival." (PMID 33767994, 2021).
metabolic disorders (3 papers, 2024 to 2025). "Hence, controlling IGFBP7 levels could be an important strategy for improved health in metabolic disease." (PMID 39280605, 2024).
bacterial infections (1 paper, 2020). "In addition, positive signals were found in the branchial epithelium of gills, suggesting that Hdh IGFBP7 might be synthesized in epithelial cells and then mixed with humoral fluid for protecting animals against bacterial infections." (PMID 32906674, 2020).
psychiatric disorder (1 paper, 2022). A disorder characterized by behavioral and/or psychological abnormalities, often accompanied by physical symptoms. "The purpose of this study was to assess whether the alterations in IGF-2 and IGFBP-7 in SZ patients are intrinsically related to the psychiatric disorder itself or are a secondary phenomenon due to antipsychotic treatment." (PMID 36076984, 2022).
IGFBP7 also shares sentences with these, for which no sentence is quoted: ischemia (4 papers); stomach cancer (4); ischemic heart disease (3); soft tissue sarcoma (3); Barrett esophagus (2); cardiomyopathies (2); Cognitive impairment (2); coronary artery atherosclerosis (2); End Stage Renal Disease (2); familial retinal arterial macroaneurysm (2); Hyperglycemia (2); injury (2); kidney cancer (2); kidney failure (2); prostate neoplasm (2); sarcoma (2); varicocele (2); acute coronary syndrome (1); aortic valve disease (1); Arrhythmia (1); artery stenosis (1); Arthritis (1); asthma (1); B-cell lymphoma (1); babesiosis (1); bacterial sepsis (1); benign tumors (1); chronic atrophic gastritis (1); chronic obstructive pulmonary disease (1); cyst (1).
A further 58 diseases each share a sentence with IGFBP7 in 1 paper.